RAP1A (RAP1A, member of RAS oncogene family)
Diseases named in the same sentence as RAP1A in open-access papers (continued):
Sharing a sentence is not in itself a finding about the gene and the disease.
melanoma (3 papers, 2021 to 2025). A malignant, usually aggressive tumor composed of atypical, neoplastic melanocytes. "Decreased survival was observed in primary melanoma cells following RAP1A knockdown, while metastatic melanoma cells showed increased proliferation rates." (PMID 40226609, 2025). "We found that Rap1a is a direct target gene of miR-2478 in melanoma cells and melanocytes." (PMID 34831071, 2021). "In this work, we found that DHCR24 and DHCR24-induced 27HC significantly upregulated Rap1A/Rap1B expression and further activated the PI3K/AKT signaling pathway in melanoma spheroids, while Rap1 agonists or AKT inhibitors reproduced the stem cell phenotypes." (PMID 38775844, 2024). "Finally, we confirmed that the effects of cholesterol on melanoma resistance require its metabolite 27HC through CYP27A1 catalysis, and that 27HC further upregulates Rap1A/Rap1B expression and increases AKT phosphorylation." (PMID 38775844, 2024). "We found that dafadine-A did not affect the proliferation of adherent melanoma cells, but dramatically inhibited cholesterol-induced melanoma spheroid propagation, with downregulation of Rap1A/Rap1B expression and phosphorylated AKT1-thr308/309." (PMID 38775844, 2024). "Because the function of Rap1a in melanoma cells has not been elucidated yet, we investigated this function in relation to whitening." (PMID 34831071, 2021).
myeloma (3 papers, 2012 to 2025). "Concerning myeloma cells, in order to detect the unprenylated form of Rap1A, longer times of in vitro treatments and higher concentrations were required." (PMID 23533771, 2013). "Consistent with our previous observation in human myeloma cells, ZA increased the amount of non-prenylated Rap1A dose-dependently and decreased prenylated Rab6 at high concentration." (PMID 23173040, 2012). "Since our study demonstrated that ZA treatment of human myeloma cells increases the abundance of the non-prenylated form of Rap1A and decreases the prenylated form of Rab6, thus we treated 5TGM1 mouse myeloma cells with increased concentration of ZA as a positive control." (PMID 23173040, 2012).
non-small cell lung carcinoma (3 papers, 2012 to 2025). A group of at least three distinct histological types of lung cancer, including non-small cell squamous cell carcinoma, adenocarcinoma, and large cell carcinoma. "The overexpression of RAP1A significantly attenuates the inhibitory effect of miR-501-3p on the proliferation and motor ability of non-small cell lung cancer cells." (PMID 39859536, 2025). "Accordingly, knock-down of Rap1A increased sensitivity to taxol in non-small cell lung cancer." (PMID 27602951, 2016).
oral cavity squamous cell carcinoma (3 papers, 2017 to 2021). A squamous cell carcinoma arising from the oral cavity. "Rap-1A pathway is also associated with survival, tumor progression, and metastasis of oral cavity squamous cell carcinoma patients." (PMID 29156751, 2017). "Recent clinical studies reported that RAP1A also correlated with the clinical characteristics of the advanced tumor stage in Oral Cavity Squamous Cell Carcinoma (OCSCC)." (PMID 34178637, 2021). "We found RAP1A level was significantly correlated with T stage, which is partly in accordance with a recent study regarding its clinical significance in oral cavity squamous cell carcinoma." (PMID 30064475, 2018).
pancreatic cancer (3 papers, 2020 to 2022). "In pancreatic cancer cells, miR-142-5p has been found to target Ras-related protein Rap-1A (RAP1A) to downregulate p-ERK1/2 and phosphate p38 mitogen-activated protein kinases (p-p38) and control cell proliferation and apoptosis." (PMID 32047668, 2020).
prostate carcinoma (3 papers, 2015 to 2021). A carcinoma that arises from epithelial cells of the prostate gland. "The same strategy of targeting protein geranylgeranylation slows tumor development in a murine model of prostate cancer metastasis possibly through reduction in Rap1A geranylgeranylation and reduces adrenal gland tumor burden in a murine model of prostate cancer metastasis." (PMID 33572160, 2021).
type 2 diabetes (3 papers, 2018 to 2025). "Therefore, we hypothesized that Rap1a crosses the AGE/RAGE cascade to alter the expression of AGE/RAGE associated signaling proteins in cardiac fibroblasts in type 2 diabetic mice." (PMID 33806572, 2021).
atherosclerosis (2 papers, 2022 to 2025). A disease characterized by the build-up of fatty material and calcium deposition in the arterial wall resulting in partial or complete occlusion of the arterial lumen. "Together, these findings redefine the roles of Rap1A and Rap1B in endothelial biology and highlight their relevance in diseases such as tumor angiogenesis, atherosclerosis, and inflammatory lung injury." (PMID 40508181, 2025).
Babesia infections (2 papers, 2015 to 2022). "Both sbp-2 and rap-1a genes have been employed as good markers for establishing phylogeographic patterns on the large scale and beneficial for epidemiological study of babesiosis." (PMID 36523637, 2022). "The significant sequence heterogeneity in different variants of the rap-1a gene from Chinese B. bovis isolates might be a great threat to the cattle industry if RAP-1a protein is used as immunological antigen against Babesia infections in China." (PMID 26452623, 2015). "Taken together, the data presented in this study suggest that the high sequence heterogeneity in the rap-1a gene from Chinese B. bovis isolates might be a great threat to the cattle industry, if RAP-1a protein is used as immunological antigen against Babesia infections in China." (PMID 26452623, 2015).
breast tumors (2 papers, 2013 to 2023). "Since the Ral guanine exchange factor, RalGDS, strongly associates with β-arrestins and Rap1A GTPases, we determined if the expression of Rap1A was also altered in patient breast tumors." (PMID 23405264, 2013). "A recent study showed that RAP1A is overexpressed in breast tumors, especially in ductal carcinoma and invasive tissues, compared to normal breast tissues." (PMID 36895029, 2023). "We found that Rap1A mRNA levels are higher in human breast tumors compared to healthy patient samples and Rap1A is robustly expressed in human ductal carcinoma in situ and invasive tumors, in contrast to the normal mammary ducts." (PMID 23405264, 2013). "Here we show that Rap1A is aberrantly expressed in human breast tumors." (PMID 23405264, 2013).
cardiac hypertrophy (2 papers, 2015 to 2025). "RAGE (receptor for advanced glycation end-products), Rap1a (RAS-related protein 1A), and AngII (angiotensin II) form an interconnected signaling network that promotes to cardiac hypertrophy, inflammation, and fibrosis." (PMID 41294886, 2025).
diabetes (2 papers, 2021 to 2022). "There is very little information regarding the role of Rap1a in diabetes-induced AGE/RAGE signaling." (PMID 33806572, 2021). "Previous studies have shown that targeting Rap1A and inhibiting T cells infiltration alleviate diabetic peripheral neuropathic pain in mice, and Rap1B may prevent excessive vascular leakage in patients with early diabetes through suppressing VEGF signaling." (PMID 36467890, 2022). "The data presented within this manuscript highlight the impact of Rap1a with acute AGE exposure on RAGE signaling proteins but does not address the impact of chronic AGE exposure, which is a characteristic of those with diabetes." (PMID 33806572, 2021).
heart failure (2 papers, 2024 to 2025). Inability of the heart to pump blood at an adequate rate to meet tissue metabolic requirements. "In conclusion, ONSMP has a dose-dependent role in heart failure therapy and regulation of molecular mechanisms, and its modulation of the cAMP/Rap1A signaling pathway is superior to that of CAP." (PMID 38402401, 2024). "In summary, ONSMP has significant advantages in improving myocardial fibrosis in heart failure by regulating the cAMP/Rap1A signaling pathway." (PMID 38402401, 2024). "This research shows that ONSMP can inhibit myocardial fibrosis and delay heart failure through the cAMP/Rap1A signaling pathway." (PMID 38402401, 2024). "It is thus clear that the mechanism by which ONSMP inhibits myocardial fibrosis in heart failure may be related to its regulation of the cAMP/Rap1A signaling pathway." (PMID 38402401, 2024). "Collectively, these results identify Rap1a and RAGE as interrelated regulators of hypertensive cardiac remodeling and potential therapeutic targets for human heart failure with preserved ejection fraction (HFpEF)." (PMID 41294886, 2025).
Insulin resistance (2 papers, 2018 to 2025). Increased resistance towards insulin, that is, diminished effectiveness of insulin in reducing blood glucose levels. "Our study demonstrates that the significantly changed expression of RAP1A, SESTRIN3, and IRS1 in PA-mTORC1-Akt pathway causes insulin resistance in T2DM macaques." (PMID 40878918, 2025). "Transcriptome results identified many DEGs linked to insulin resistance, fatty acid β oxidation, and inflammation, including IGF2BP2, LEPR, RAP1A, SESTRIN 3, and ITLN1 that have also been reported in human T2DM." (PMID 40878918, 2025). "Genetic ablation or pharmacologic inhibition of neuronal RAP1A gene in mice reduces insulin resistance, improves leptin sensitivity in the hypothalamus and protects from dietary obesity." (PMID 30573851, 2018).
Kabuki syndrome (2 papers, 2024). Kabuki syndrome (KS) is a multiple congenital anomaly syndrome characterized by typical facial features, skeletal anomalies, mild to moderate intellectual disability and postnatal growth deficiency. "Recent studies have identified additional genes associated with Kabuki syndrome, including RAP1A, RAP1B, and HNRNPK." (PMID 38667491, 2024). "RAP1A and RAP1B dysfunction results in aberrant MEK/ERK signaling, indicating an overlap in the pathophysiology of Kabuki syndrome caused by these genes and the RASopathies." (PMID 38667491, 2024). "Thus, a comprehensive screening of other genes associated with Kabuki syndrome (e.g., KDM6A, RAP1A, RAP1B, and HNRNPK) was not performed." (PMID 38667491, 2024).
anemia (1 paper, 2024). A reduction in the number of red blood cells, the amount of hemoglobin, and/or the volume of packed red blood cells. "A complete blood count (CBC) was performed to assess the overall health of Rap1A knock-out (−/−) versus wild-type (+/+) mice, particularly for evidence of anemia and effect on hemoglobin level." (PMID 39125590, 2024).
autism spectrum disorder (1 paper, 2025). A spectrum of developmental disorders that includes autism, and Asperger syndrome. "With respect to neurodevelopmental disorders, Rap1a has been associated with autism spectrum disorder." (PMID 41488750, 2025).
autoimmune thyroiditis (1 paper, 2025). "Patients with increased I exposure experience hypomethylation of most of the CpG locus of RAB8A, olfactory receptor family 4 subfamily K member 17 (OR4K17), and RAP1A, indicating that excess I is involved in the pathogenesis of autoimmune thyroiditis." (PMID 39940256, 2025). "The study from 2023 showed that autoimmune thyroiditis is correlated to hypomethylation of Ras-related protein Rab-8A (RAB8A) and Ras-related protein Rap-1A (RAP1A), which corresponded to higher levels of mRNA expression." (PMID 39940256, 2025).
bladder cancer (1 paper, 2006). "Here, we found that YM529 blocks the prenylation of Rap1A and Ras in bladder cancer cells, inhibits the growth of bladder cancer cells in vitro, in a dose- and time-dependent manner, and clearly induces apoptosis in bladder cancer cells." (PMID 17043684, 2006). "Then, we investigated the alteration of Rap1A status in bladder cancer cells by YM529." (PMID 17043684, 2006).
cardiomyopathy (1 paper, 2022). A disease of the heart muscle or myocardium proper. "The components of the MAPK pathway, such as MAP2K1 through MAPK3, as well as the Ras-related proteins, RAP1A, RAP1B, and M-Ras, had a median 2.6-fold (IQR, 2.0-fold to 15.5-fold) upregulation among patients with SARS-CoV-2 infection compared with patients with noninflammatory cardiomyopathy." (PMID 34910083, 2022).
cerebral cavernous malformation (1 paper, 2024). A disorder characterized by malformations in the structure of the capillaries in the brain. "Subsequently named Krev1/Rap1a Interaction Trapped, Krit1 was mapped initially to chromosome 7q21-22, where a gene mutated in Cerebral Cavernous Malformations (CCM) had recently been mapped." (PMID 38980708, 2024).
choroidal neovascularization (1 paper, 2013). An eye disorder described by the growth of new blood vessels that originate from the choroid through a break in the Bruch membrane into the sub–retinal pigment epithelium (sub-RPE) or subretinal space. "In a laser-induced choroidal neovascularization (CNV) model of macular degeneration, Rap1b−/− mice exhibited larger CNV volumes compared to wild-type or Rap1a−/−." (PMID 24039860, 2013).
colon cancer (1 paper, 2015). "The data further suggest that although VGSCs signal through both Rap1A and Rap1B in colon cancer cells, Rap1B activation in particular leads to persistent ERK1/2 MAPK activation." (PMID 26096612, 2015). "Thus, we investigated the participation of Rap1 in the VGSC signaling in colon cancer cells and found that VGSCs signal through both Rap1A and Rap1B to increase invasion potential." (PMID 26096612, 2015).
epilepsy (1 paper, 2017). A brain disorder characterized by episodes of abnormally increased neuronal discharge resulting in transient episodes of sensory or motor neurological dysfunction, or psychic dysfunction. "As for our predicted candidates, it has been confirmed that, during the pathological processes of epilepsy, the normal function of RAP1A and its related Ras signaling pathway has been regulated and altered by microRNAs, implying the potential role of Ras signaling pathway during epilepsy." (PMID 28255556, 2017).
fatty liver (1 paper, 2025). "RAP1A plays a role in liver inflammation and fibrosis, and the activation of RAP1A could protect against fatty liver and MASLD development." (PMID 39941272, 2025).
focal segmental glomerulosclerosis (1 paper, 2022). A renal disorder characterized by sclerotic lesions in the glomeruli. "In mice, knockout of Rap1A and Rap1B results in disruption of slit diaphragm integrity and development of focal segmental glomerulosclerosis (FSGS)." (PMID 35372328, 2022). "In mice, knockout of Rap1A and Rap1B results in disruption of slit diaphragm integrity and development of focal segmental glomerulosclerosis (FSGS)—a chronic glomerular disease with scarring, sclerotic lesions." (PMID 35372328, 2022).
head and neck squamous cell carcinoma (1 paper, 2020). A squamous cell carcinoma that arises from any of the following anatomic sites: lip and oral cavity, nasal cavity, paranasal sinuses, pharynx, larynx, and salivary glands. "In prostate and head and neck squamous cell carcinoma (HNSCC), Rap1A has been shown to promote invasion and migration of tumor cells." (PMID 32906721, 2020).
hyperlipidemia (1 paper, 2015). "The hyperlipidemia compensatory effect of statin therapy could be observed for few proteins, three of them being involved in both actin cytoskeleton and focal adhesion regulation pathways: alpha-actinin-1, transforming protein RhoA and integrin alpha-1 besides the ras-related protein Rap-1A." (PMID 26628893, 2015).
ischaemia (1 paper, 2025). "Roles for Rap1a have been identified in cerebral ischaemia injury, cerebral and spinal cord cavernomas, multiple sclerosis, and refractory epilepsy." (PMID 41488750, 2025).
leukemia (1 paper, 2011). A malignant (clonal) hematologic disorder, involving hematopoietic stem cells and characterized by the presence of primitive or atypical myeloid or lymphoid cells in the bone marrow and the blood. "Remaining candidates (N = 62) comprised BDNF-related genes (SST), MAPK-pathway genes (KRAS, IGF1R, GNG11 and RAP1A), genes related with leukemia (SFRP1) and Rho-Proteins (DHCR7 and RAB21)." (PMID 21569303, 2011).
lymph node metastasis (1 paper, 2018). "In the multivariate analysis, we found RAP1A expression and lymph node metastasis were independent prognostic factors for OS, while RAP1A expression, lymph node metastasis and preoperative CEA level were for DFS (all p < 0.05)." (PMID 30064475, 2018). "In the univariate analysis, we found RAP1A expression, lymph node metastasis and preoperative CEA level were significant prognostic factors for both OS and DFS (all p < 0.05)." (PMID 30064475, 2018).
Macrothrombocytopenia (1 paper, 2022). "Simultaneous loss of Rap1a and Rap1b further prolongs bleeding times; it also causes macrothrombocytopenia due to impaired platelet production." (PMID 35290242, 2022).
medulloblastoma (1 paper, 2021). A malignant, invasive embryonal neoplasm arising from the cerebellum. "Only two of them (RAP1A–TMIGD3 and ZSWIM5P2–MEIS3) occurred in both the WNT and SHH subtype as well as in group 3 and group 4 medulloblastoma." (PMID 34830991, 2021).
Obesity (1 paper, 2019). Accumulation of substantial excess body fat. "MRNA levels of Rap1a and Rap1b were unaffected by diet-induced obesity whereas expression of Rab3a was slightly reduced." (PMID 31337827, 2019).
ovarian endometriosis (1 paper, 2022). A non-neoplastic disorder characterized by the growth of endometrial tissue in the ovaries. "It has been found that RAP1A and EPAC1 were highly expressed in ovarian endometriosis and their expressions were positively correlated, speculating that RAP1A and EPAC1 may cooperate with each other to participate in the occurrence and development of EMs and in the regulation of dysmenorrhea." (PMID 35281615, 2022).
sarcoma (1 paper, 2018). A usually aggressive malignant neoplasm of the soft tissue or bone. "For instance, in sarcoma virus-transformed NIH/3T3, middle T antigen-transformed Rat-2 cells, and keratinocytes, Rap1a/1b were found to inhibit cell proliferation, partially by suppressing Ras pathway." (PMID 29599749, 2018).
squamous cell carcinoma (1 paper, 2013). A carcinoma arising from squamous epithelial cells. "Although the specific mechanisms by which Rap1A mediates cell invasion are unclear, Rap1A has been shown to stimulate MMP-7 gene transcription in squamous cell carcinoma cells via β-catenin." (PMID 23405264, 2013).
tuberous sclerosis (1 paper, 2021). Hereditary disease characterized by seizures, intellectual disability, developmental delay, and skin and ocular lesions. "This has been seen in tuberous sclerosis, where the tuberin/hamartin complex loses its inhibitory impact on Rheb signaling while losing its stimulatory impact on the guanosine triphosphatase (GTPase)-activating protein for Krev-1=rap1a." (PMID 34824953, 2021).